PARK7 (Parkinsonism associated deglycase)
Diseases named in the same sentence as PARK7 in open-access papers (continued):
Sharing a sentence is not in itself a finding about the gene and the disease.
prostate carcinoma (14 papers, 2011 to 2025). A carcinoma that arises from epithelial cells of the prostate gland. "PARK7 undergoes upregulation in prostate cancer cells and reducing its expression significantly diminishes proliferation and survival." (PMID 35317831, 2022). "PARK7 induces the transcriptional activity of the ARs and is used as a biomarker of prostate cancer." (PMID 32357493, 2020). "The overexpression of PARK7 protects prostate cancer cells from apoptosis via the inhibition of tumor necrosis factor-related apoptosis-inducing ligand (TNFSF10) that acts as a specific inducer of apoptosis." (PMID 32357493, 2020). "PARK7 significantly increases the growth of prostate cancer in patients receiving androgen deprivation therapy as neoadjuvant hormone therapy in >6 months." (PMID 32357493, 2020). "A study reported that ARs are the interacting partners of PARK7 in prostate cancer cells, and hormonal treatment enhances the formation of PARK7/AR complexes." (PMID 32357493, 2020). "Mutations in DJ1 (PARK7, a regulator of the tumor suppressor PTEN) is observed in PD patients and in breast, lung, pancreatic, gastric and prostate cancers." (PMID 29255414, 2017). "Furthermore, PARK7 acts as a regulatory subunit of an RNA binding protein and is upregulated in 86% of patients with prostate cancer and closely correlated with reduced survival of prostate cancer patients and in prostate cancer cells." (PMID 32357493, 2020). "In this way, PARK7 overexpression inhibits MAPK/JNK signaling to prevent BECN1-BCL2 dissociation, resulting in autophagy inhibition and paving the way for prostate cancer progression." (PMID 35317831, 2022). "PARK7 (DJ-1) was reported overexpressed in the non-small-cell lung cancer (NSCLC) and prostate cancer cell line." (PMID 26245297, 2015).
Cerebral ischemia (13 papers, 2009 to 2024). Restriction of arterial blood supply to the brain associated with insufficient oxygenation to support the metabolic requirements of the tissue. "Furthermore, Park7 could inhibit ferroptosis in cerebral ischemia-reperfusion injury via the Atf4/Hspa5 pathway." (PMID 39343514, 2024).
Huntington disease (13 papers, 2014 to 2025). Huntington disease (HD) is a rare neurodegenerative disorder of the central nervous system characterized by unwanted choreatic movements, behavioral and psychiatric disturbances and dementia. "The increased amount of overoxidized form of PARK7/DJ-1 was reported in the brain of patients with several neurodegenerative disorders, namely AD, PD, and Huntington’s disease." (PMID 36672187, 2023). "On the contrary, the reduced expression and/or the increased amount of dysfunctional overoxidized form of PARK7/DJ-1 was found in the brain of patients with various neurodegenerative disorders, including PD, AD, Huntington’s disease, and ischemic stroke." (PMID 35743072, 2022).
ischemia (13 papers, 2009 to 2024). A hypoperfusion of the BLOOD through an organ or tissue caused by a PATHOLOGIC CONSTRICTION or obstruction of its BLOOD VESSELS, or an absence of BLOOD CIRCULATION. "The protective effect of PARK7 signaling was identified in renal tubular epithelial cell injury induced by ischemia." (PMID 32194432, 2020).
type 2 diabetes (13 papers, 2012 to 2025). "PARK7 protects pancreatic beta-cells from oxidative stress conditions, and its deficiency is associated with decreased inflammatory and adipogenesis responses and type 2 diabetes." (PMID 38760690, 2024).
dementia (11 papers, 2011 to 2025). Loss of intellectual abilities interfering with an individual's social and occupational functions. "Owing to the report regarding the association between dementia and protein misfolding, we also assessed the level of serum misfolding proteins such as alpha-synuclein and PARK7 in order to probe for the possible underlying mechanism in memory enhancement." (PMID 40724595, 2025). "Two proteins in our panel, NGF and Parkinson disease protein 7 (PARK7), have well-established connections to brain function and dementia." (PMID 37759795, 2023). "In other forms, such as those caused by recessive mutations in the parkin (PARK2), PINK1 (PARK6), DJ-1 (PARK7), and ATP13A2 (PARK9), the phenotype is more often atypical due to younger-onset, presence of additional clinical signs (dementia, pyramidal signs), or absence of Lewy body-pathology." (PMID 21347293, 2011). "In our NGS study, we identified RDVs in genes which were previously associated with other neurodegenerative disorders with or without dementia, such as C19ORF12, PRKN, LRRK2, and PARK7 genes in three patients (P81, P35, P50)." (PMID 35752680, 2022).
non-small cell lung carcinoma (11 papers, 2011 to 2024). A group of at least three distinct histological types of lung cancer, including non-small cell squamous cell carcinoma, adenocarcinoma, and large cell carcinoma. "Functional proteomic profiling identified PARK7 as a novel molecular target of non-small cell lung carcinoma (NSCLC)." (PMID 32357493, 2020).
ischemic stroke (10 papers, 2015 to 2023). A stroke disorder caused by obstruction of blood flow to the brain, due to thrombotic (local blood clot formation) or embolic (due to a blood clot or other material traveling from another site) event. "A well-established protective role of PARK7/DJ-1 has been demonstrated in ischemic stroke and neurodegenerative diseases such as PD and AD." (PMID 37238925, 2023). "Parkinson’s disease 7 (PARK7/DJ-1) is a multifunctional protein whose protective role has been widely demonstrated in neurodegenerative diseases, including PD, AD, or ischemic stroke." (PMID 35743072, 2022). "The ROC curve analysis showed that serum PARK7 and UFDP levels had some diagnostic value on the phlegm-heat syndrome in ischemic stroke patients." (PMID 26539220, 2015). "In addition, pharmacological activation of PARK7/DJ-1 was neuroprotective in animal models of PD, AD, and ischemic stroke, as well." (PMID 35743072, 2022).
colon cancer (8 papers, 2018 to 2023). "It is reported that the decrease in the expression of PARK7/DJ-1 induces an inflammatory response in colon cancer cells, indicating its anti-inflammatory effect." (PMID 37868345, 2023). "Cell division cycle 5-like (Cdc5l) protein has been shown to promote hTERT expression and colorectal tumor growth, while metastasis biomarker Park7/DJ-1 is known to promote colon cancer by stimulating Wnt-β-catenin signaling." (PMID 32973493, 2020). "In our previous study, we have revealed that PARK7 is associated with colon cancer invasion and progression, but the role of ATP13A2 in colon cancer initiation and progression remains unknown." (PMID 33308286, 2020). "We found that the mRNA levels of ATP13A2 and PARK7 were significantly higher in colon cancer tissue than in normal tissue." (PMID 33308286, 2020).
Dystonia (8 papers, 2013 to 2025). An abnormally increased muscular tone that causes fixed abnormal postures. "Mutations in the protein DJ-1, encoded by the PARK7 gene, cause early-onset autosomal recessive forms of PD with dystonia and psychiatric symptoms, and oxidized DJ-1 was found in the brains of idiopathic PD individuals." (PMID 38069350, 2023). "In PD patients, rare large genomic duplications or deletions have also been observed in the PD genes SNCA (PARK1), Parkin (PARK2), and DJ1 (PARK7) and in a gene that causes dystonia/infantile parkinsonism, tyrosine hydroxylase (TH)." (PMID 24073418, 2013).
glioblastoma (8 papers, 2013 to 2025). The most malignant astrocytic tumor (WHO grade IV). "The expression of PARK7 is negatively associated with the expression of the epithermal growth factor receptor, which correlates with the poor differentiation of glioblastoma cells." (PMID 32357493, 2020). "Additionally, the expression of PARK7 is upregulated in 85% of patients with glioblastoma and 48.5% of patients with medulloblastoma." (PMID 32357493, 2020).
inflammatory bowel disease (8 papers, 2020 to 2024). A spectrum of small and large bowel inflammatory diseases of unknown etiology. "Several regulatory mechanisms are hypothesized, including methylation of the promoter probe cg10385390 (chr1:8’022’505) increasing the risk for inflammatory bowel disease by reducing PARK7 expression." (PMID 36477627, 2022). "Genetic instruments for PARK7, GPX1, and MST1 were linked to various digestive system disorders including sclerosing cholangitis and inflammatory bowel disease." (PMID 38887235, 2024). "Involvement of the anti-oxidant and anti-inflammatory protein PARK7 in inflammatory bowel disease (IBD) has recently been brought to light." (PMID 36477627, 2022). "Interestingly, rs35675666 is located in the first intron of the PARK7 transcript and is a GWAS SNP for ulcerative colitis (P = 5 × 10−9) and inflammatory bowel disease (P = 1 × 10−15)." (PMID 32665975, 2020).
male infertility (8 papers, 2013 to 2021). The inability of the male to effect fertilization of an ovum after a specified period of unprotected intercourse. "Defects in Parkinsonism-associated protein 7 (Park7, also known as DJ-1), an oxidative stress response product, have been widely reported to be correlated with male infertility." (PMID 34344298, 2021). "DJ-1, a conserved protein product of the PARK7 gene, is associated with male infertility and plays a role in oxidative stress and inflammation." (PMID 29849492, 2018). "It is highly conserved in a variety of mammalian tissues, and mutations or deletions in PARK7 have been found associated with many diseases, including male infertility." (PMID 29849492, 2018). "Human DJ-1 is a causative gene of PARK7-linked familial PD and plays a role in resisting oxidative stress as well as being related to male infertility in human studies." (PMID 23894418, 2013). "DJ-1 is a ubiquitously expressed protein encoded by PARK7 gene, initially identified as an oncogene functionally associated with cancer and male infertility." (PMID 23983902, 2013).
Glucose intolerance (7 papers, 2015 to 2022). Glucose intolerance (GI) can be defined as dysglycemia that comprises both prediabetes and diabetes. "Park7 expression increases in pancreatic islets of an aged mouse or human, protecting the mitochondrial integrity and avoiding the development of glucose intolerance and reduced β‐cell area." (PMID 36149763, 2022).
colitis (6 papers, 2021 to 2025). Inflammation of the colon. "Fas-associated protein with death domain (FADD) and PARK7 have been reported in relation to colitis." (PMID 34746064, 2021). "Effect of PARK7 on the synthesis of IBD related cytokines was determined using PARK7 gene silenced HT-29 cells and 3,4,5-trimethoxy-N-(4-(8-methylimidazo(1,2-a)pyridine-2-yl)phenyl)benzamide (Comp23)—compound increasing PARK7 activity—treated mice with DSS-colitis." (PMID 34272410, 2021). "Parkinson's disease protein 7 (PARK7) deficiency leads to increased apoptosis in colitis and has been proposed as a therapeutic target for colitis but has never been linked to NEC." (PMID 34746064, 2021). "Therefore, further investigating the effect of IL-17 on the PARK7 synthesis we found that while it increased in the colon of DSS treated WT mice, it remained unchanged in the colon of Il17−/− mice with DSS induced colitis." (PMID 34272410, 2021). "In this study we report the presence, regulation and role of PARK7 in the pathomechanism of mucosal inflammation using tissue samples of therapy-naive children with IBD, and in vitro and in vivo experimental models of colitis." (PMID 34272410, 2021). "Considering that in our experiments Park7 gene silencing did not alter expression of Il10, we suggest that decreased colonic expression of Il10 may be rather an indirect consequence of decreased inflammation, observed in Comp23 treated mice with DSS induced colitis." (PMID 34272410, 2021).
Dyskinesia (6 papers, 2019 to 2025). A movement disorder which consists of effects including diminished voluntary movements and the presence of involuntary movements. "A deletion and missense mutation in the DJ1 (PARK7, Chromosome 1p36) leads to an inherited, autosomal recessive, early onset form of PD, that presents with dyskinesia, rigidity, tremors, and later decline in cognitive function." (PMID 34356159, 2021). "Genetic factors are more commonly observed in LD‐induced dyskinesias, such as LRRK2, PARK2 (parkin), PARK6 (pink‐1), and PARK7 (DJ‐1)." (PMID 40785408, 2025).
glioma (6 papers, 2020 to 2025). A benign or malignant brain and spinal cord tumor that arises from glial cells (astrocytes, oligodendrocytes, ependymal cells). "In our study, a protein–protein interaction (PPI) network analysis was conducted using the GeneMANIA database to further evaluate the potential roles of DJ-1 (PARK7), GDF15, and MFGE8 genes in glioma and meningioma pathogenesis." (PMID 41009755, 2025). "PARK7 was significantly increased in both GBM and GIV sample groups, relative to controls and RECQL was a top-50 DE plasma-EV protein, with high levels distinguishing GIV from GIII gliomas (10.7-fold, adj." (PMID 32635403, 2020). "The expression levels of EMB, LDHA, SLC16A1, SLC16A3, SLC16A8, PARK7, and PFKFB2 were lower in 1p/19q Codel glioma than those in non-Codel glioma." (PMID 36698888, 2022).
injury (6 papers, 2018 to 2022). Damage inflicted on the body as the direct or indirect result of an external force, with or without disruption of structural continuity. "For instance, PARK7 is highly expressed in lipopolysaccharides-induced acute lung injury, while decreased in heavy smoking-induced lung disease." (PMID 34093596, 2021). "This is notable because GSTP1 and PARK-7 play an important antioxidant role following brain injury." (PMID 30274397, 2018). "Therefore, our results suggest that PARK7 may be a potential therapeutic target for APAP-induced acute liver injury." (PMID 36358500, 2022). "However, how PARK7 regulates mitochondrial quality control in APAP-induced acute liver injury has not been studied." (PMID 36358500, 2022).
Insulin resistance (6 papers, 2015 to 2023). Increased resistance towards insulin, that is, diminished effectiveness of insulin in reducing blood glucose levels. "Recent studies indicate that exosomes produced by adipocytes from insulin-resistant subjects contain proteins that are strongly associated with insulin resistance and T2D, such as calreticulin, S100A6, mimecan, PARK7/DJ1, PPIB, and tenascin." (PMID 34299048, 2021). "PARK7 participates in glucose homeostasis and then induces insulin resistance." (PMID 37293508, 2023).
Lewy body dementia (6 papers, 2019 to 2025). A progressive form of dementia characterized by the presence of protein deposits called Lewy bodies in the midbrain and cerebral cortex, and loss of cholinergic and dopaminergic neurons. "As PARK7 is suggested to cause dementia with Lewy bodies (DLB), the coexistence of variants in C19ORF12 and PARK7 is assumed to contribute to the symptoms of P50." (PMID 35752680, 2022).
renal fibrosis (6 papers, 2020 to 2025). A final common manifestation of a wide variety of chronic kidney diseases characterized by glomerulosclerosis and tubulointerstitial fibrosis. "We thus determined the effect of Park7 deficiency on the levels of ROS in renal tubules during UUO-induced renal fibrosis by dihydroethidium (DHE) staining." (PMID 34093596, 2021). "Third, we provided further evidence that Park7 deficiency or knockdown aggravated ROS accumulation, tubular cell apoptosis, and inflammation in renal fibrosis models." (PMID 34093596, 2021). "In vivo, Park7 deficiency aggravated UUO-induced renal fibrosis, as manifested by more severe tubular atrophy and kidney deposition of extracellular matrix proteins in Park7 ko mice than in WT mice following UUO." (PMID 34093596, 2021). "PARK7 decreased markedly in atrophic kidney tubules in UUO mice, and Park7 deficiency aggravated UUO-induced renal fibrosis, tubular cell apoptosis, ROS production and inflammation." (PMID 34093596, 2021). "In addition, the protein most strongly associated with G2 in contrast to G1 was Park7, a multifunctional protein that reduces oxidative stress and was suggested to protect against renal fibrosis in other conditions." (PMID 40536813, 2025). "Second, we demonstrated that Park7 deficiency aggravated UUO-induced renal fibrosis in mice." (PMID 34093596, 2021). "Collectively, these findings indicate that PARK7 is protective against tubular cell apoptosis and inflammation during renal fibrosis." (PMID 34093596, 2021). "In the present study, we provided evidence that PARK7 has an important role in scavenging ROS and thereby reduces cell death and inflammation in kidneys during renal fibrosis." (PMID 34093596, 2021). "Mechanistically, we showed that during renal fibrosis, PARK7 accumulated in the nucleus in renal tubular cells, and positively regulated expression of the antioxidant enzyme SOD2." (PMID 34093596, 2021). "In the present study, we have provided substantial evidence supporting a renoprotective role of renal tubular cell PARK7 in renal fibrosis." (PMID 34093596, 2021). "Taken together, these results indicate that PARK7 protects against chronic kidney injury and renal fibrosis by inducing SOD2 to reduce oxidative stress in tubular cells." (PMID 34093596, 2021). "Our present study has provided evidence supporting a beneficial role of renal tubular PARK7 in renal fibrosis." (PMID 34093596, 2021). "In summary, this study provide evidence that PARK7 in renal tubular cells is renoprotective during renal fibrosis through suppressing ROS accumulation, cell apoptosis and inflammation." (PMID 34093596, 2021). "However, PARK7 oxidation and its contribution to PARK7 degradation during renal fibrosis remain to be determined." (PMID 34093596, 2021). "However, the pathophysiological role and mechanism of PARK7 in the pathogenesis of renal fibrosis remain largely unclear." (PMID 34093596, 2021). "Collectively, these findings suggest that PARK7 may protect against renal fibrosis by reducing ROS and suppressing cell death." (PMID 34093596, 2021). "Together, these findings suggest a protective function of PARK7 in chronic kidney injury and renal fibrosis, and accordingly, enhancement of PARK7 expression and/or activity may represent a promising therapeutic approach." (PMID 34093596, 2021). "Collectively, these findings suggest that PARK7 may protect against chronic kidney injury and renal fibrosis by inducing SOD2 and reducing ROS and oxidative stress." (PMID 34093596, 2021). "Thus, prevention of ROS accumulation via enhancing intracellular PARK7 levels and/or activity represents potential therapeutic strategies for renal fibrosis." (PMID 34093596, 2021). "Thus, PARK7 plays an important role in scavenging ROS in renal tubules during renal fibrosis." (PMID 34093596, 2021).
renal fibrosis (continued). "In the present study, by using a unilateral ureteric obstruction (UUO)-induced mouse model of renal fibrosis, and culturing renal TECs exposed to TGFB1, we demonstrated that PARK7 protects against renal TIF and related kidney injury by inducing SOD2 and scavenging ROS." (PMID 34093596, 2021).